CRTAC1 (cartilage acidic protein 1)
Synonyms: CEP-68; ASPIC1; FLJ10320; ASPIC; LOTUS
Tractability: Antibody: UniProt places it where antibodies can reach, with high confidence; UniProt predicts a signal peptide or a membrane-spanning region; its Gene Ontology location is reachable by antibodies, with medium confidence. PROTAC: its protein half-life has been measured.
Gene: Protein-coding gene on chromosome 10 (97,865,000 to 98,030,828, reverse strand). Ensembl gene ENSG00000095713.
Subcellular location: Secreted, extracellular space, extracellular matrix
Gene Ontology:
Molecular function: protein binding; calcium ion binding
Biological process: axonal fasciculation; regulation of synapse assembly
Cellular component: extracellular exosome; glutamatergic synapse; growth cone; postsynaptic density
Genetic constraint (gnomAD): Loss-of-function variants: 38 observed, 64.46 expected, observed/expected ratio (o/e) 0.59, 90% interval 0.45 to 0.77. The upper end of that interval is the gene's LOEUF score, 0.77, which puts it in group 3 of 6, group 1 being the genes least tolerant of losing a copy. Missense variants: 780 observed, 917.84 expected, observed/expected ratio (o/e) 0.85, 90% interval 0.8 to 0.9. Synonymous variants: 348 observed, 365.58 expected, observed/expected ratio (o/e) 0.95, 90% interval 0.87 to 1.04.
Homologues: Orthologues: chimpanzee CRTAC1 (99% identical), macaque CRTAC1 (98% identical), dog CRTAC1 (94% identical), rat Crtac1 (92% identical), pig CRTAC1 (90% identical), rabbit CRTAC1 (89% identical), guinea pig CRTAC1 (88% identical), mouse Crtac1 (88% identical), tropical clawed frog crtac1 (74% identical), zebrafish crtac1b (66% identical), zebrafish crtac1a (56% identical).
Diseases named in the same sentence as CRTAC1 in open-access papers:
CRTAC1 is named in the same sentence as 33 diseases in open-access papers, as found by Europe PMC text mining. Sharing a sentence is not in itself a finding about the gene and the disease. The quoted sentences say what the papers report.
bladder cancer (6 papers, 2020 to 2025). "First, the result of Pearson correlation analysis indicated that the expression of CRTAC1 was negatively associated with YY1 in the tissues of bladder cancer patients." (PMID 34818994, 2021). "Then, the function of CRTAC1 in bladder cancer cells in vitro was explored by a series of gain/loss-of-function assays." (PMID 34818994, 2021). "CRTAC1 overexpression inhibits cell proliferation, migration, invasion and EMT process, and CRTAC1 deficiency promotes these malignant behaviors of bladder cancer cells." (PMID 34818994, 2021). "According to the survival analysis from Kaplan-Meier Plotter, high CRTAC1 expression are associated with better prognosis in patients with bladder cancer." (PMID 34818994, 2021). "The study explored the functions and underlying mechanism of CRTAC1 in bladder cancer." (PMID 34818994, 2021). "The study may expand our knowledge of the function and underlying mechanism of CRTAC1 in bladder cancer." (PMID 34818994, 2021). "However, the functions and underlying mechanism of CRTAC1 in bladder cancer have been rarely explored." (PMID 34818994, 2021). "High CRTAC1 expression are associated with better prognosis in patients with bladder cancer." (PMID 34818994, 2021). "Low tumor levels of CRTAC1 are predictive of a poor prognosis in various cancers, including bladder cancer, gastric cancer, lung cancer, and low‐grade glioma." (PMID 40517318, 2025). "Consistent with this, CRTAC1 promoter hypermethylation has been observed in bladder cancer and lung adenocarcinoma." (PMID 40517318, 2025). "Patients with high CRTAC1 expression levels exhibit a more favorable prognosis in bladder cancer and glioma with respect to those whose expression levels are low9,10." (PMID 38755183, 2024). "CRTAC1, one of the pyroptosis-related genes, has been identified as a protective factor in certain kinds of cancer, such as gastric adenocarcinoma and bladder cancer." (PMID 38755183, 2024). "Several prior studies have demonstrated that patients with decreased CRTAC1 expression exhibit an unfavorable prognosis in glioma, bladder cancer, and gastric adenocarcinoma." (PMID 38755183, 2024). "It turned out that CRTAC1 is of interest for bladder cancer since it inhibits many pro-tumorigenic processes including cell viability and migration." (PMID 35563688, 2022). "Rescue assays indicated that CRTAC1 inhibited malignant behaviors of bladder cancer cells by targeting YY1." (PMID 34818994, 2021). "Cell models with high or low level of CRTAC1 were established in bladder cancer cell lines (T24,5637) respectively." (PMID 34818994, 2021). "YY1 overexpression reverses the suppressive effect of CRTAC1 overexpression on malignant behaviors of bladder cancer cells." (PMID 34818994, 2021). "Overall, CRTAC1 inhibited malignant phenotypes of bladder cancer cells by targeting YY1 to inactivate the TGF-β pathway." (PMID 34818994, 2021). "Gain-of-function experiments and loss-of-function experiments were conducted to explore the effect of silenced or overexpressed CRTAC1 on malignant phenotypes of bladder cancer cells." (PMID 34818994, 2021). "Based on bioinformatics analyses, CRTAC1 expression is decreased in tissue samples of bladder urothelial carcinoma and its low expression correlates with poor survival in patients with bladder cancer." (PMID 34818994, 2021). "Cartilage acidic protein 1 (CRTAC1) is predicted to be aberrantly expressed in bladder cancer based on bioinformatics analysis." (PMID 34818994, 2021). "Our work revealed that CRTAC1 is downregulated in bladder cancer tissues and cells, and CRTAC1 inhibits cell proliferation, migration, invasion and EMT process as shown by functional experiments." (PMID 34818994, 2021). "In the current study, we found that the expression of CRTAC1 was decreased in bladder cancer tissue samples and cell lines." (PMID 34818994, 2021).
bladder cancer (continued). "In conclusion, CRTAC1 inhibits bladder cancer cell proliferation, migration, invasion and EMT by targeting YY1 to inactivate the TGF-β signaling pathway." (PMID 34818994, 2021). "In the present study, we demonstrated that YY1 activated the TGF-β signaling while CRTAC1 inhibited the activation of TGF-β signaling by targeting YY1 in bladder cancer cells." (PMID 34818994, 2021). "The study aimed to investigate the role of CRTAC1 in the development of bladder cancer." (PMID 34818994, 2021). "We hypothesized that CRTAC1 might affect malignant behaviors of bladder cancer cells by regulating the expression of downstream target genes." (PMID 34818994, 2021). "CRTAC1 overexpression decreased the mRNA and protein levels of YY1, while CRTAC1 deficiency showed opposite effects on YY1 expression, which indicated that CRTAC1 negatively regulated YY1 expression in bladder cancer cells." (PMID 34818994, 2021). "Moreover, RT-qPCR and western blotting also revealed the downregulation of CRTAC1 in bladder cancer cell lines compared with that in normal urothelial cell line SVHUC-1." (PMID 34818994, 2021). "Mechanistically, CRTAC1 targeted YY1 in bladder cancer cells." (PMID 34818994, 2021). "Mechanistically, CRTAC1 directly targets YY1 in bladder cancer cells." (PMID 34818994, 2021). "We hypothesized that CRTAC1 might affect malignant phenotypes of bladder cancer cells by regulating its downstream target gene." (PMID 34818994, 2021). "CRTAC1 is downregulated in bladder cancer tissues and cells." (PMID 34818994, 2021). "The result of RT-qPCR showed that CRTAC1 was lowly expressed in the bladder cancer tissues." (PMID 34818994, 2021). "Subsequently, we investigated the downstream regulatory mechanism of CRTAC1 in bladder cancer." (PMID 34818994, 2021). "We found that CRTAC1 was downregulated in bladder cancer tissues and cells." (PMID 34818994, 2021). "This study aimed to explore the role of CRTAC1 in bladder cancer." (PMID 34818994, 2021). "Moreover, rescue experiments implied that CRTAC1 inhibits malignant behaviors of bladder cancer cells by downregulating YY1." (PMID 34818994, 2021). "Second, the function of CRTAC1 on bladder cancer progression in vivo needed further investigation." (PMID 34818994, 2021). "We then explored whether CRTAC1 regulated the TGF-β signaling in bladder cancer cells." (PMID 34818994, 2021). "According to Immunofluorescent staining and Co-IP assays, colocalization of CRTAC1 and YY1 was identified in the nucleus of bladder cancer cells." (PMID 34818994, 2021). "In summary, CRTAC1 inhibits cell proliferation, migration, invasion and EMT process in bladder cancer by downregulating YY1 to inactivate the TGF-β pathway." (PMID 34818994, 2021). "The expression of CRTAC1 and YY1 was negatively correlated with each other in the tissue samples of bladder cancer." (PMID 34818994, 2021). "Moreover, we explored whether CRTAC1 regulated YY1 level in bladder cancer cells." (PMID 34818994, 2021). "YY1 overexpression was revealed to reverse the inhibitory effect of upregulated CRTAC1 on TGF-β signaling and bladder cancer cell viability, proliferation, migration, invasion and EMT process." (PMID 34818994, 2021). "Overall, CRTAC1 inhibits cell proliferation, migration, invasion and EMT process in bladder cancer by downregulating YY1 to inactivate the TGF-β pathway." (PMID 34818994, 2021). "Then, the expression and colocalization of CRTAC1 and YY1 in the nucleus of bladder cancer cells was visualized by immunofluorescent staining assay." (PMID 34818994, 2021). "Additionally, mRNA and protein expression of YY1 was decreased by CRTAC1 overexpression and increased by CRTAC1 knockdown, which indicated that CRTAC1 negatively regulated YY1 expression in bladder cancer cells." (PMID 34818994, 2021). "CRTAC1 negatively modulated the mRNA and protein expression of YY1 in bladder cancer cells." (PMID 34818994, 2021).
bladder cancer (continued). "First, the upstream regulatory mechanism of CRTAC1 was not explored in bladder cancer cells." (PMID 34818994, 2021).
COVID-19 (6 papers, 2021 to 2024). A disease caused by infection with severe acute respiratory syndrome coronavirus 2. "Down-regulated genes showed lower fold changes than the up-regulated genes, including cartilage acidic protein 1, CRTAC1, (log2FC = −4.16), previously known to be down-regulated in COVID-19 patients with severe infection." (PMID 36768969, 2023). "From these proteins CRTAC1, IGLV3-1, HRG, HSPB1, LCP1, ITIH3, and APOA2 have all been identified as correlating with COVID-19 in other research, but to our knowledge, the rest are novel." (PMID 37308820, 2023). "Traditionally, CRP has been used as a systemic clinical marker of inflammation in COVID-19 and other diseases, although the SROC curves suggest that other acute phase proteins, such as ORM1, CRTAC1, SERPINA3, TF, and AHSG might perform better as biomarkers of inflammation." (PMID 37739942, 2023).
lung adenocarcinoma (6 papers, 2022 to 2025). A carcinoma that arises from the lung and is characterized by the presence of malignant glandular epithelial cells. "Above all, the expression of CRTAC1 may hold significant diagnostic and prognostic implications for lung adenocarcinoma." (PMID 38755183, 2024). "The mRNA expression of CRTAC1 was lower in lung adenocarcinoma than in normal tissues, and reduced expression levels were associated with poor prognosis." (PMID 40076501, 2025). "Lastly, the results derived from migration and invasion experiments demonstrated a noteworthy decrease in the migratory and invasive potential of lung adenocarcinoma cells following the overexpression of CRTAC1." (PMID 38755183, 2024). "Our study suggested that overexpression of CRTAC1 can effectively inhibit the invasion and migration of lung adenocarcinoma cells." (PMID 38755183, 2024). "Our research examined the impact of regulating CRTAC1 expression levels on the proliferation of lung adenocarcinoma cells." (PMID 38755183, 2024). "The study aimed to investigate the role of CRTAC1 in lung adenocarcinoma (LUAD)." (PMID 38755183, 2024). "They used gene expression data analysis from public databases to find that CRTAC1 expression was lower in lung adenocarcinoma (LUAD) than in normal tissues, demonstrating that the CRTAC1 gene was a protective gene in LUAD, and the high expression of CRTAC1 gene had a better prognosis." (PMID 35847844, 2022).
osteoarthritis (6 papers, 2020 to 2025). A noninflammatory degenerative joint disease occurring chiefly in older persons, characterized by degeneration of the articular cartilage, hypertrophy of bone at the margins and changes in the synovial membrane. "Elevated blood CRTAC1 levels are associated with poor outcomes in patients with acute ischemic stroke and osteoarthritis." (PMID 40517318, 2025). "Joint tissues contribute significantly to plasma CRTAC1 concentration as demonstrated by population‐wide proteomic studies that associate higher plasma CRTAC1 concentrations with severity and progression of osteoarthritis." (PMID 37667413, 2023). "CRTAC1 can be used as a biomarker for osteoarthritis severity and progression via plasma proteomics analysis, demonstrating the role of CRTAC1 and related diverse pathways in chondrocyte pathologies." (PMID 39158018, 2024). "Indeed, in a small intensity‐based mass spectrometric study, a 5.5‐fold increase in CRTAC1 was found in osteoarthritis patients versus controls." (PMID 37667413, 2023). "IL-1β and TNF-α in patients with osteoarthritis can induce and obviously upregulate the expression of CRT in articular chondroblasts or synovial fibroblasts, CRTAC1 can be used as a biomarker to distinguish chondrocytes from osteoblasts and mesenchymal stem cells." (PMID 36507532, 2022).
glioma (5 papers, 2020 to 2025). A benign or malignant brain and spinal cord tumor that arises from glial cells (astrocytes, oligodendrocytes, ependymal cells). "Patients with LUAD, BLCA and LGG with low expression of CRTAC1 have poor prognosis, which is consistent with that found in glioma." (PMID 33195408, 2020). "In addition to CRTAC1 as a tumor suppressor gene, other genes could have a pro-oncogenic function in patients with glioma." (PMID 35839032, 2022). "CRTAC1, an extracellular matrix protein initially isolated from human chondrogenic tissue, was found to be present at lower levels in the plasma of glioma patients compared with nonglioma patients, and in glioma tissue compared with tumor‐free brain tissue." (PMID 40517318, 2025). "Currently, there is no study revealing the role of SEMA4G and CRTAC1 in gliomas." (PMID 31921517, 2020).
lung carcinoma (3 papers, 2023 to 2025). "Downregulation of CRTAC1 expression in lung cancer tissues predicts a poor prognosis, suggesting that it can act as a tumor suppressor." (PMID 37633993, 2023). "Furthermore, in the lung cancer cohort, lower CRTAC1 expression was in connection with advanced pathologic stage (p = 0.004), pathologic T stage (p = 0.006), and pathologic N stage (p = 0.03)." (PMID 38755183, 2024). "However, the current understanding of the involvement of CRTAC1 in the pathogenesis of lung cancer remains incomplete." (PMID 38755183, 2024).
gastric cancer (2 papers, 2022 to 2025). A primary or metastatic malignant neoplasm involving the stomach. "However, the role of CRTAC1 has not yet been reported in STAD or other gastric cancer." (PMID 35619651, 2022).
idiopathic pulmonary fibrosis (2 papers, 2022 to 2023). Idiopathic pulmonary fibrosis (IPF) is a nonneoplastic pulmonary disease that is characterized by the formation of scar tissue within the lungs in the absence of any known cause. "CRTAC1 is decreased in plasma and bronchoalveolar lavage (BAL) of patients with idiopathic pulmonary fibrosis, a finding that has been attributed to loss of expression of CRTAC1 by de‐differentiated T2AE cells." (PMID 37667413, 2023). "Proteomic analysis of plasma and BAL CRTAC1 of patients with idiopathic pulmonary fibrosis identified CRTAC1 as one of a small set of circulating proteins that is enriched in BAL when compared to plasma." (PMID 37667413, 2023). "Loss or de‐differentiation of T2AE cells is hypothesized to explain the decrease in plasma and bronchoalveolar lavage fluid CRTAC1 in pulmonary fibrosis." (PMID 37667413, 2023). "Analysis of cultured T2AE cells and single‐cell transcriptomic and proteomic data from pulmonary fibrosis patients and recent human expression atlases indicate that T2AE cells are a major source of CRTAC1." (PMID 37667413, 2023). "Interestingly, a recent study reported that the CRTAC1 protein levels in lung lavage fluid and blood plasma is a novel peripheral protein biomarker of the lung alveolar epithelial health status reflecting the de-differentiation of AT2 cells in lung fibrosis." (PMID 35628257, 2022).
non-small cell lung carcinoma (2 papers, 2023 to 2024). A group of at least three distinct histological types of lung cancer, including non-small cell squamous cell carcinoma, adenocarcinoma, and large cell carcinoma. "Jin’s research indicated that the potential of CRTAC1 to augment the chemosensitivity of non-small cell lung cancer to cisplatin is attributed to its ability to induce RyR-mediated calcium release and suppress Akt1 expression." (PMID 38755183, 2024).
adenoma (1 paper, 2025). A neoplasm arising from the epithelium. "The expression of Vnn1 and Crtac1 was further enhanced by neonatal irradiation, which may have contributed to the transition from hyperplasia to adenoma observed in the 1w12Gy group." (PMID 40076501, 2025).
bladder urothelial carcinoma (1 paper, 2024). "For example, TFAP2A has been reported to reduce the expression of CRTAC1 by promoting TPRG1-AS1 transcription, thereby accelerating glycolysis and angiogenesis in bladder urothelial carcinoma (BLCA) and promoting the progression of BLCA." (PMID 39695171, 2024).
cardiomyopathies (1 paper, 2024). "Four variants, c.302G>C/p.Gly101Ala (CAPN1), c.637C>T/p.Arg213Trp (MTUS2), c.457C>T/p.Arg153Cys (CRTAC1), c.1309G>T/p.Gly437Cys (UNC45A), were associated with cardiomyopathies." (PMID 38848015, 2024).
cataract (1 paper, 2021). Partial or complete opacity of the crystalline lens of one or both eyes that decreases visual acuity and eventually results in blindness. "Moreover, a high level of CRTAC1 plays an important role in pyroptosis in cataracts, while the downregulation of CRTAC1 significantly attenuates UVB-induced pyroptosis." (PMID 34925047, 2021).
chronic obstructive pulmonary disease (1 paper, 2023). A chronic and progressive lung disorder characterized by the loss of elasticity of the bronchial tree and the air sacs, destruction of the air sacs wall, thickening of the bronchial wall, and mucous accumulation in the bronchial tree. "CRTAC1 concentrations below those of controls were found in some patients a year after hospitalization with COVID‐19, long COVID after less severe COVID‐19, or chronic obstructive pulmonary disease." (PMID 37667413, 2023).
gastric adenocarcinoma (1 paper, 2024). "Shen's research indicated that the CRTAC1 mutation rate in gastric adenocarcinoma is a mere 2%, with missense mutation being the most prevalent form of gene alteration." (PMID 38755183, 2024).
malnutrition (1 paper, 2023). Inadequate nutrition resulting from poor diet, malabsorption, or abnormal nutrient distribution. "TFAP2A promotes angiogenesis and glycolysis in bladder uroepithelial carcinoma (BLCA) by disrupting cartilage acidic protein 1 (CRTAC1) expression when exposed to hypoxia and malnutrition." (PMID 37291585, 2023).
Respiratory distress (1 paper, 2023). Respiratory distress is objectively observable as the physical or emotional consequences from the experience of dyspnea. "Here we report using a sensitive sandwich ELISA to determine plasma CRTAC1 concentration in our original cohort of patients hospitalized for respiratory distress during the first weeks of the COVID‐19 pandemic, healthy controls, COPD, and patients recovering from COVID‐19." (PMID 37667413, 2023).